EPCAM (epithelial cell adhesion molecule)
Diseases named in the same sentence as EPCAM in open-access papers (continued):
Sharing a sentence is not in itself a finding about the gene and the disease.
tumor (continued). "In this study, our system did not rely on tumor cell biomarkers such as epithelial markers (EpCAM, cytokeratins) or mesenchymal markers (vimentin, N-cadherin, E-cadherin)." (PMID 37849806, 2023). "The presence of disseminating tumour cells that express EpCAM but not CD24 did not correlate with metastasis." (PMID 37975646, 2023). "Higher expression of EpCam and KRT19 in tumor tissues confirmed that they were malignant." (PMID 36865791, 2023). "Staining for EpCAM and CD24 alongside the mesenchymal marker Vimentin in over 12,000 imaging fields from 74 human tumours, stratified on metastatic status, identifies cells that have undergone EMT and disseminated into the stromal region surrounding metastatic primary tumours." (PMID 37975646, 2023). "EPCAM+ cells display similar levels of CD73 expression in both NCL and tumor tissue." (PMID 37648263, 2023). "On the other hand, EpCAM is likely available for co-stimulation on most tumor tissues while the presence on healthy tissues should not be harmful due to lack of primary signaling through the CAR as long as CEA is not expressed." (PMID 38169746, 2023). "The results indicated that targeting EpCAM and Wnt/β-catenin can inhibit tumor growth and enhance tumor infiltration without affecting T-cell survival, promoting the efficacy of EpCAM CAR T-cell therapy." (PMID 36707873, 2023). "Among them, PSMA, EpCAM (epithelial cellular adhesion molecule), and MUC1 (mucin-1) are three representative targets for aptamer selection using the purified-protein-based SELEX, and for tumor-targeted delivery of aptamer-functionalized nanoparticles." (PMID 37544972, 2023). "In vivo, EpCAM-gated HT-29 tumor cells harvested from non-reconstituted mice did not express HLA-II, whereas HT-29 tumor cells from HIS mice showed HLA-II expression (0.1% vs. 6% respectively, p = 0.03)." (PMID 37185301, 2023). "EpCAM is a specific epithelial marker, that is not expressed in stromal or immune cells – it is expressed exclusively in epithelia and epithelial-derived tumours." (PMID 37975646, 2023). "We demonstrated that GCEPs have self-renewal capacity, tumor formation capacity, and differentiation potential in vitro, thereby producing cells with different surface markers derived from single cells with the CD24+CD44+CD54+EpCAM+ phenotype." (PMID 36737794, 2023). "The results showed that tumor cells with the high expression level of EpCAM were sensitive to the BsAb but not to parental EpCAM mAb." (PMID 35281893, 2022). "A previous study has found that HCC with low expression levels of stemness-related markers, such as keratin 19 or epithelial cell adhesion molecule (EpCAM), could show better outcomes after TACE, such as fewer residual tumors and more complete tumor necrosis." (PMID 35111225, 2022). "Similarly, low EpCAM expression enhanced EMT of cancer cells and was correlated with advanced tumor stage and lymph node metastasis in endometrial carcinoma." (PMID 36369033, 2022). "Conventionally-defined CTCs are defined by their expression of tumor-specific proteins (e.g., cytokeratin (CK) or epithelial cellular adhesion molecule (EpCAM) in epithelial malignancies), and the absence of the pan-leukocyte marker, CD45." (PMID 36010865, 2022). "While cell surface PD-L1 expression was observed on the tumor-associated myeloid cells (CD45+, monocytes and dendritic cells), it was absent on the tumor cells (CD45−, EPCAM+)." (PMID 35760778, 2022). "Interestingly, in our study, the expression of AFP, YAP, GRP78, and EpCAM was attenuated in the livers from Stk25-/- mice, supporting the importance of STK25 not only in the development of HCC but also in tumor progression." (PMID 34624527, 2022). "In papillary thyroid carcinoma, lncRNA BANCR is responsible for maintaining stemness and tumor growth via the c-RAF/MEK/ERK pathway; additionally, it is observed to influence the expression of CSC markers LGR5 and EpCAM, this eventually leads to tumor development." (PMID 36359888, 2022).
tumor (continued). "Moreover, a significant positive correlation was found between EpCAM/CD166 phenotypes expression and tumor stage (P = 0.03), tumor differentiation (P = 0.05), neural, and lymph node invasion (P =0.01)." (PMID 35016698, 2022). "Additionally, through the analysis of exosomes, more and more tumor-related biomarkers have been found, such as HER2, EpCAM, MUC1, CA125, and so on." (PMID 36235208, 2022). "In terms of tumor stage, 45 (69%), 109 (69.5%), 11 (55%), 32 (47%), 31 (52%), 6 (40%), and 12 (63.5%) of stage I, IIA, IIB, IIIA, IIIB, IIIC, and IVA displayed higher expression of EpCAM, respectively (P = 0.007)." (PMID 35016698, 2022). "These were PanCk, a marker for tumor epithelium, HER2, EPCAM, and B7-H3." (PMID 36230846, 2022). "Selecting for EpCAM+ve CTCs only might miss the detection of other CTC populations in E-to-M transition states and the opportunity to obtain a full picture of the tumor plasticity and in response to therapy." (PMID 36428760, 2022). "First, CICs were isolated from the tumor sphere-propagated cells from colorectal human specimens and colorectal xenograft (SQ) tumors by FACS sorting using several of the previously reported candidates (CD44v6, CD133, EpCAM and ALDH1)." (PMID 36330477, 2022). "Removal of CTCs by the functionalized nanoparticles should result from an EpCAM epitope-antibody interaction and not from the non-specific binding of tumor cells to the surface of the nanoparticles." (PMID 35890293, 2022). "Specifically, biological methods use antibodies against specific tumor biomarkers, such as EpCAM, which is not expressed in blood cells but only in cells of an epithelial origin." (PMID 36230554, 2022). "The targeted nanocarriers showed significantly different impacts on cells that were positive or negative for the EpCAM marker, indicating selective anti-tumor activity of our formula." (PMID 36686226, 2022). "With its widely application in basic and translational research, however, minimal or no expression of EpCAM is found on circulating tumor cells (CTCs) in some cancer patients." (PMID 36077658, 2022). "Non-PTS KRT14+ epithelial/tumor cells uniquely expressed known BCC-associated gene biomarkers including BCAM and EPCAM." (PMID 35687691, 2022). "Moreover, in nude mice injected with EpCAM+ HCC cells, a strong inhibition of tumor growth was achieved when 5-fluorouracil (5-FU) and OSM were administered together." (PMID 36077744, 2022). "To validate the absence of tumor cells in our samples, we performed immunocytochemistry against EpCAM." (PMID 36010660, 2022). "EpCAM is expressed in tumor cells but not in normal cells found in the peritoneal cavity lining and fluids (mesothelial cells, leukocytes, and macrophages)." (PMID 35740397, 2022). "Despite a flurry of related studies that have shown positive or negative links between EpCAM and tumor progression, few studies involve the specific cellular mechanism of EpCAM and its functional consequences." (PMID 35517503, 2022). "In tumor cells isolated from primary HCC tissues, pearson correlation analysis revealed that MUC15 levels were negatively correlated with the expression of CD24 and EpCAM." (PMID 35236826, 2022). "Through cell annotation, we found that CD45+ immune cells, but not EPCAM+ tumor cells, constituted the dominant cell subset in TET tumors." (PMID 36115836, 2022). "Because of the toxicity of ROR1-targeted CAR-T cells attributable to ROR1 expression in normal tissues, CAR-T cells have been engineered with synthetic Notch receptors EpCAM and B7-H3 to improve selectivity, specificity, and tumor regression in ROR1-expressing tumor cells with less toxicity." (PMID 35720364, 2022). "However, treatment with EpCAM antibodies seems to decrease PD-L1 protein levels and increase the activity of cytotoxic CD8+ TILs in vitro and in mouse tumor models." (PMID 35158964, 2022).
tumor (continued). "Since EpCAM and HGF/c-Met are involved in important signaling pathways in various cancers, the purpose of this study is to elucidate the interplay between these molecules, tumor microenvironment, and intracellular pathways." (PMID 35986321, 2022). "The number of CSCs with the EpCAM+CD44+MET+CD47+ phenotype increased with tumour progression, while no significant changes were found in the number of CSCs representing the main population of tumour cells." (PMID 35563449, 2022). "For instance, CAR-T cells targeting the Mullerian inhibiting substance type 2 receptor (MISIIR), B7-H3, Epithelial cell adhesion molecule (EpCAM), C-X-C chemokine receptor 1 (CXCR1), or C-X-C chemokine receptor 2 (CXCR2), 5T4 significantly controlled tumor growth in vivo." (PMID 36275669, 2022). "EpCAM (CD326 or ESA) plays an important role in the migration and metastasis of tumour cells." (PMID 35563449, 2022). "HCC cells expressing EpCAM have more excellent stem cell features, tumour formation and invasion ability than those not expressing EpCAM." (PMID 35152538, 2022). "Besides, VB4-845, an inhibitor targeting EpCAM+ CSCs in HCC, showed effective anti-tumor cytotoxicity and synergistic effects in combination with 5-FU." (PMID 36293184, 2022). "The molecular mechanisms of the tumor suppressive function of EpCAM in these cancers are not yet clear." (PMID 35975801, 2022). "EpCAM-based affinity separation cannot be applied to CTCs with weakly expressed or nonexpressed EpCAM in the process of tumor cell metastasis, which leads to the significant decrease or even loss of EpCAM expression." (PMID 36090904, 2022). "A link was also seen between EpCAM and CD166 that represented co-expression of two markers (P = 0.02) and a significant direct correlation between EpCAM/CD166 phenotypes expression and tumor stage (P = 0.03), tumor differentiation (P = 0.05), neural, and lymph node invasion (P =0.01) in CRC tissues." (PMID 35016698, 2022). "When blood samples from healthy donors were analyzed with the Attune CytPix, EpCAM+EGFR+ events showed no tumor cell-like morphology." (PMID 36613466, 2022). "Thus, for an EpCAM-specific DARPin-MMAF conjugate fused to either XTEN or PAS sequences, an intermediate size and half-life of the conjugates showed the strongest anti-tumor effects." (PMID 35630749, 2022). "Previous results from our group, showed that NSCLC stem cells, the CD133+/CXCR4+EpCAM subset, was triggered by EMT, an event that can be induced by stimuli from the tumor microenvironment, able to convert progenitor cells into cancer stem cells, endowed with invasiveness ability." (PMID 35563517, 2022). "In addition, we performed fluorescence-activated cell sorting (FACS) analysis of EPCAM+ cells or GPC3+ cells for three HCC samples with available cryopreserved single-cell suspension, because the two markers were known elevated in tumor cells." (PMID 36476645, 2022). "Interestingly, there was a significant positive correlation between EpCAM/CD166 phenotypes expression and tumor stage (P = 0.03), tumor differentiation (P = 0.05), neural, and lymph node invasion (P =0.01)." (PMID 35016698, 2022). "Isolation methodologies based on EpCAM such as CellSearch® are widely used, although elevated EpCAM expression levels were only found in metastatic HCC lesions compared to primary and vascular invaded tumor." (PMID 36518850, 2022). "Markers may vary depending on the type of tumor, but most CSCs carry CD133, CD44, CD90, CD34, aldehyde dehydrogenase 1 (ALDH)-1, epithelial cell adhesion molecule (EpCAM) and other stem cell markers on their surface." (PMID 36613838, 2022).
tumor (continued). "Our study showed that 49% of the pan-CK-positive objects were EpCAM-negative, of which the majority expressed other tumor markers in addition to pan-CK, including AR, PSA and PSMA." (PMID 33801459, 2021). "Thirdly, several publications have demonstrated a higher metastasizing potential for EpCAM positive carcinoma cells compared to EpCAM negative tumor cells." (PMID 34715784, 2021). "An FDA-approved system (CELLSEARCH® Circulating Tumor Cell Kit–Menarini Silicon Biosystems Inc, Bologna, Italy) utilizes EpCAM and cytokeratins (CK8, CK18, and CK19) in CD45 negative circulating cells." (PMID 34572776, 2021). "To search for clinically relevant circulating tumor cell (CTC) epitopes, we first co-stained the CD45-negative (CD45−) fraction of CRC blood samples from 13 patients with our potential CTC marker, CD44v6, and the known CTC marker EpCAM." (PMID 34638450, 2021). "Secondly, also EpCAM negative tumor cells will be reduced up to 90% due to centrifugation and filtration steps independent of the binding and crosslinking ability of the trifunctional antibody (filter characteristics)." (PMID 34715784, 2021). "The majority of electrochemical sensors in the last five years has focused on detection of EpCAM in serum and blood, rather than the tumor microenvironment." (PMID 34439139, 2021). "As such, a role for WT EpCAM in the regulation of CTSL in normal epithelia and/or cancer (as demonstrated here) is consistent with the known roles for EpCAM in the regulation of both epithelial-to-mesenchymal transition (EMT) and tumor cell invasion." (PMID 33980181, 2021). "The current study demonstrates that CEA and EpCAM have an absent or low expression (TIS < 6) in the tumor bed of nearly all patients with a pCR after neoadjuvant therapy." (PMID 33799475, 2021). "Along with the trajectory, epithelial cell marker EPCAM and ductal marker KRT19 exhibited sustained high expression levels during PDAC progression, while genes previously reported to be involved in tumor progression, such as MUC1 and CEACAM6, gradually upregulated along with the transition." (PMID 34732701, 2021). "EpCAM is related to several signaling pathways including the intramembrane protein hydrolysis (RIP)-mediated signaling and the activation of Wnt signaling to impact on tumor cell proliferation." (PMID 34922633, 2021). "In the contrary, non-responder frequently showed the high level of phospho-Rb (Ser807/811) in western blot and tissue staining, and also displayed the intense EpCAM in the tumor cells which were not altered after irradiation." (PMID 33767581, 2021). "Regarding the tumor cells, all dissociated tumors from all three patients contained cells expressing EpCAM and CD47, with and without positive CD56 expression." (PMID 33670410, 2021). "The first is a proliferative/cycling epithelial-like state acquired through mesenchymal-epithelial transition (MET) that is characterized by the expression of ALDH, E-cadherin and epithelial cell adhesion molecule (EPCAM); these cells are usually located more centrally within the tumor mass." (PMID 34638263, 2021). "Treatment with LDN‐212854 suppressed HCC tumor growth by repressing ID1 and EpCAM in vivo." (PMID 33834612, 2021). "Although the CellSearch system has been widely used to detect CTCs depending on tumor cell epithelial markers such as EpCAM and CK, it fails to detect CTCs undergoing EMT." (PMID 35127528, 2021). "Moreover, in metastatic PC, numerous circulating tumor cells (CTCs) can express mesenchymal (vimentin, N-cadherin and O-cadherin), stem cells (CD133), and epithelial cell (E-cadherin, epithelial cell adhesion molecule (EpCAM), and cytokeratins) markers." (PMID 34868907, 2021).
tumor (continued). "Moreover, miR-125b is downregulated in tumor spheres, and its reinforced expression reduces their diameter, the percentage of EpCAM and CD13-positive cells, as well as tumor initiation in vivo." (PMID 34572776, 2021). "In addition, AFP level can predict the expression of hepatic progenitor cell markers as EpCAM in HCC and is correlated with tumor metastasis." (PMID 35070966, 2021). "The tumor cells were negative for BerEP4/EpCAM, pancytokeratin AE1/AE3, cytokeratin 19, celladhesion molecule 5.2 (CAM5.2), epithelial membrane antigen (EMA), and friend leukemia virusintegration 1 (FLI1)." (PMID 34106022, 2021). "On the other hand, EpCAM could be lost during the epithelial to mesenchymal transition (EMT) process, as tumor undifferentiation leads epithelial cell lines to recover stem-cells’ characteristics, including the expression of other markers such as vimentin." (PMID 34069569, 2021). "First, we categorized clustered data into tumor and stromal populations using a panel of markers for each (epithelial: AQP1, AQP2, EPCAM; endothelial: PLVAP, CD31, CD34; fibroblast: PDGFRα, PDGFRβ; immune: CD45; tumor cell: CXCR4, VIM, KRT18, PAX8, PAX2, CA9, CD10)." (PMID 34884982, 2021). "Finally, we interrogated the GSE39396 database, which includes a wide range of cell types: epithelial (EpCAM+), endothelial (CD31+), leukocytes (CD45+), and CAFs (FAP+) isolated by FACS from tumor biopsies." (PMID 33802791, 2021). "Factors limiting clinical efficacy of EpCAM-targeting antibodies include poor penetration in tumor mass, insufficient anti-tumor action, and lack of patient stratification to identify potential responders prior to therapy." (PMID 34439094, 2021). "All six patients that were positive for HER2 expression in EpCAM(+) CTCs were negative for HER2 amplification in the primary tumor." (PMID 33799422, 2021). "During the process of dissemination and metastasis, tumor cells undergo epithelial-mesenchymal transition (EMT) and might lose their epithelial cell features including EpCAM and/or keratin expression." (PMID 34111181, 2021). "Following this strategy, our platform used negative enrichment and the canonical tumor marker EpCAM and cytokeratin, among other markers, which have been regarded as clinical standards in CTC labeling." (PMID 33301640, 2021). "It has been reported that the MCA system achieved a superior detection of CTCs, probably because it was size dependent and not EpCAM expression dependent in tumor cells, such as the CellSearch system." (PMID 33675149, 2021). "After intravesical administration of catumaxomab no EpCAM-positive tumor cells were found any more in the urine after one, respectively two treatment cycles." (PMID 33837852, 2021). "No positive staining was seen with the rabbit monoclonal SB EpCAM on any of the tested feline tumor cells." (PMID 33614766, 2021). "Moreover, the cluster of EpCAM enriched cells were also enriched for several other genes of clinical interest including APOC1, a biomarker of tumor progression, ALDH1A1, a marker of tumor cell “stemness”, and AKR1C3, a marker of doxorubicin resistance." (PMID 33989287, 2021). "First, it does not depend on the expression of tumor cell surface markers, such as EpCAM and GFAP; thus, the CTC tracer is independent of the expression levels of cell surface markers and specific molecular types." (PMID 34763698, 2021). "Our tumour compartment specific multivariate signature for response was largely consistent with the DE results, comprising higher levels of fibronectin, GZMA and STING and lower EPCAM and CD80 (AUC = 0.875)." (PMID 35083152, 2021). "Nuclear translocation of EpICD depends upon the degree of regulated intramembrane proteolysis, which affects a variable proportion rather than the totality of full‐length EpCAM molecules and can differ within tumor areas." (PMID 33340247, 2021). "EpCAM is also used for the isolation of circulating tumor cells in metastatic PTC but the antigen is not expressed on ATC cells." (PMID 34439219, 2021).